PIK3R5 (phosphoinositide-3-kinase regulatory subunit 5)
Description:
Regulatory subunit of the PI3K gamma complex. Required for recruitment of the catalytic subunit to the plasma membrane via interaction with beta-gamma G protein dimers. Required for G protein-mediated activation of PIK3CG (By similarity).
Synonyms: P101-PI3K; p101; F730038I15Rik; FOAP-2
Tractability: Small molecule: a drug acting on it is in phase 2 or 3 trials; a high-quality ligand is known. Antibody: UniProt places it where antibodies can reach, with medium confidence; its Gene Ontology location is reachable by antibodies, with medium confidence. PROTAC: ubiquitination databases record sites on it; its protein half-life has been measured; a small molecule that binds it is known.
Safety:
Unwanted effects reported when the protein is acted on. In parentheses: how it was acted on, where the effect was seen, and who reports it.
hypertension (source: ClinPGx)
Gene: Protein-coding gene on chromosome 17 (8,878,911 to 8,965,726, reverse strand). Ensembl gene ENSG00000141506.
Subcellular location: Nucleus; Cytoplasm; Cell membrane
Subcellular location (Human Protein Atlas): Cytosol; Centriolar satellite
Pathways (Reactome):
Signal Transduction: Erythropoietin activates Phosphoinositide-3-kinase (PI3K); G beta:gamma signalling through PI3Kgamma; PI5P, PP2A and IER3 Regulate PI3K/AKT Signaling; PIP3 activates AKT signaling
Immune System: CD28 dependent PI3K/Akt signaling; Co-stimulation by ICOS
Disease: Constitutive Signaling by Aberrant PI3K in Cancer
Hemostasis: GPVI-mediated activation cascade
Metabolism: Synthesis of PIPs at the plasma membrane
Gene Ontology:
Molecular function: 1-phosphatidylinositol-3-kinase regulator activity; G-protein beta/gamma-subunit complex binding
Biological process: G protein-coupled receptor signaling pathway; immune response; phosphatidylinositol 3-kinase/protein kinase B signal transduction; positive regulation of MAP kinase activity; positive regulation of phosphatidylinositol 3-kinase/protein kinase B signal transduction; phosphatidylinositol metabolic process
Cellular component: centriolar satellite; cytosol; phosphatidylinositol 3-kinase complex, class IA; cytoplasm; membrane; phosphatidylinositol 3-kinase complex; phosphatidylinositol 3-kinase complex, class IB; nucleus; plasma membrane
Genetic constraint (gnomAD): Loss-of-function variants: 27 observed, 84.15 expected, observed/expected ratio (o/e) 0.32, 90% interval 0.23 to 0.44. The upper end of that interval is the gene's LOEUF score, 0.44, which puts it in group 1 of 6, group 1 being the genes least tolerant of losing a copy. Missense variants: 832 observed, 1,113.9 expected, observed/expected ratio (o/e) 0.75, 90% interval 0.7 to 0.79. Synonymous variants: 435 observed, 465.31 expected, observed/expected ratio (o/e) 0.93, 90% interval 0.86 to 1.01.
Gene-disease validity (ClinGen):
ClinGen rates the evidence that PIK3R5 causes each of these diseases.
ataxia with oculomotor apraxia type 3 (autosomal recessive): Disputed.
Homologues: Orthologues: chimpanzee PIK3R5 (99% identical), macaque PIK3R5 (95% identical), rabbit PIK3R5 (91% identical), dog PIK3R5 (91% identical), pig PIK3R5 (90% identical), guinea pig PIK3R5 (89% identical), rat Pik3r5 (86% identical), mouse Pik3r5 (86% identical), tropical clawed frog pik3r5 (52% identical), zebrafish pik3r5 (46% identical). Paralogues in human: PIK3R6 (21% identical).